TBK1 (TANK binding kinase 1)
Diseases named in the same sentence as TBK1 in open-access papers (continued):
Sharing a sentence is not in itself a finding about the gene and the disease.
Parkinson disease (5 papers, 2020 to 2025). A progressive degenerative disorder of the central nervous system characterized by loss of dopamine producing neurons in the substantia nigra and the presence of Lewy bodies in the substantia nigra and locus coeruleus. "TBK1 phosphorylation is dependent upon Parkin, an E3 ubiquitin ligase that is associated with inherited Parkinson disease." (PMID 32969543, 2020). "The connections between Parkinson disease, Rab7 and kinases TBK1/LRRK1 require further investigation." (PMID 32969543, 2020). "Notably, elevated TBK1 was predominantly localized in the microglia of the SDH following PDN in diabetic db/db mice; the same cell localization has been reported in Parkinson’s disease model." (PMID 39030571, 2024). "Nonetheless, in patients with an autosomal dominant history of atypical parkinsonism, TBK1 should be part of any atypical parkinsonism gene panel along with MAPT and GRN, and mutations in TBK1 suspected if other family members have ALS (which would not be seen in MAPT or GRN mutations)." (PMID 32980182, 2021).
pulmonary fibrosis (5 papers, 2019 to 2026). Chronic progressive interstitial lung disorder characterized by the replacement of the lung tissue by connective tissue, leading to progressive dyspnea, respiratory failure, or right heart failure. "The IFIT3−/− mouse model shows potential benefits of targeting the IFIT3/TBK1 signalling pathway in reducing skin and lung fibrosis in the SSc mouse model." (PMID 39305055, 2024). "TBK1 knockdown or inhibition significantly ameliorates radiation-induced pulmonary fibrosis and collagen deposition." (PMID 35924048, 2022). "Inhibiting TBK1, both in cell cultures and mouse models, reversed the cell transitions and prevented pulmonary fibrosis." (PMID 30988282, 2019). "As Th1 and Th2 balance play critical roles in lung fibrosis, we further examined the impact of TBK1 depletion on the Th1/Th2 cytokine balance in BALF after irradiation." (PMID 30988282, 2019). "In conclusion, our results indicate that the TBK1–AKT–ERK signaling pathway regulates radiation-induced EMT in normal alveolar epithelial cells, suggesting that TBK1 is a potential target for pulmonary fibrosis prevention during cancer radiotherapy." (PMID 30988282, 2019). "Constructed an IFIT3−/− mouse model using clustered regularly interspaced short palindromic repeats (CRISPR)/CRISPR‐associated protein 9 (Cas9) gene editing to assess the potential benefits of intervening in the IFIT3/TBK1 signalling pathway on skin and lung fibrosis in the SSc mouse model." (PMID 39305055, 2024). "In addition to AURKA, tank‐binding protein kinase‐1 (TBK1) also plays a role in YAP/TAZ‐mediated pulmonary fibrosis, as TBK1 can stabilize YAP/TAZ protein and further promote fibroblast activation." (PMID 37576865, 2023). "TBK1 knockdown or inhibition significantly reversed EMT in vivo and in vitro and attenuated pulmonary fibrosis and collagen deposition." (PMID 30988282, 2019).
Sepsis (5 papers, 2022 to 2025). Sepsis is defined as life-threatening organ dysfunction caused by a dysregulated host response to infection. "In this study, we found that 67% H2 inhalation inhibited the activation of STING during sepsis, thereby reducing the phosphorylation of TBK1 and IRF3 and thus reducing the level of neuroinflammation." (PMID 40016173, 2025). "It has been demonstrated that EGFR regulates the inflammatory function of macrophages, and EGFR can also induce the apoptosis of CD4(+) T lymphocytes through the TBK1/Glut1-induced Warburg effect in sepsis." (PMID 38632608, 2024). "In sepsis, EGFR can induce the apoptosis of CD4 + T lymphocytes by promoting the Warburg effect through TBK1/Glut1 signaling pathway." (PMID 38632608, 2024). "We found that GUP inhibited the activation of the cGAS-STING pathway by inhibiting the interaction of STING with TBK1 and TBK1 with IRF3, thereby reducing the harm of sepsis." (PMID 38904004, 2024). "Western blot analysis revealed that in the LPS-induced sepsis model (Group 2), Nogo-A expression was significantly elevated, while the expression of proteins such as p-PERK, MFN1, NOX2, NOX4, NLRP3, p-STING, p-TBK1, and IL-1β also significantly increased, and SHP2 expression decreased." (PMID 39151100, 2024). "The levels of STING, p‐TBK1, and p‐IRF3 in the hippocampus of mice in the CLP group were significantly greater than those in the Sham group indicating that the STING‐TBK‐IRF3 pathway in the hippocampus was activated during sepsis, which can further trigger neuroinflammation." (PMID 40016173, 2025). "Although we demonstrated that STING directly induces ferroptosis in a manner dependent on its interaction with NCOA4 but independent of cGAS or TBK1 in lethal sepsis, whether the role of STING upon iron metabolism orchestrates immune homeostasis still requires further investigation." (PMID 35902564, 2022). "Interestingly, we discovered that STING-mediated macrophage ferroptosis in sepsis does not rely on the classical elements of the STING pathway, including cGAS, TBK1, and cytokines transcription from NF-κB." (PMID 35902564, 2022).
steatosis (5 papers, 2013 to 2025). Increased lipid within the cytoplasm of cells. "Macrophage Foxo1 deficiency (Foxo1M-KO) ameliorated hepatic inflammation, steatosis, and fibrosis, with reduced STING, TBK1, and NF-κB activation in HFD-challenged livers." (PMID 39122845, 2024). "Collectively, these results demonstrate that TBK1 kinase activity is progressively diminished during the transition from steatosis to MASH, particularly within hepatocyte mitochondria, highlighting a potential mechanistic link between TBK1 dysfunction and the exacerbation of MASH pathogenesis." (PMID 41282122, 2025).
type 1 diabetes (5 papers, 2008 to 2024). "In this study, through chemical screens using the zebrafish model of type 1 diabetes, we identified TBK1/IKKε inhibitors (TBK1/IKKε-Is) as enhancers of β-cell regeneration." (PMID 30349097, 2018). "Taken together, these results indicate that suppression of TBK1/IKKε augments β-cell regeneration in the zebrafish model of type 1 diabetes." (PMID 30349097, 2018). "In this study, we identified TBK1/IKKε-Is as selective enhancers of β-cell regeneration in a transgenic zebrafish model of type 1 diabetes." (PMID 30349097, 2018). "Recently, inhibitors of TBK1/IKKε were shown to function as enhancers of β-cell regeneration through a whole organism small molecule screening in a transgenic zebrafish model of type 1 diabetes (T1D) where β-cells are specifically ablated using a chemical-genetic ablation method." (PMID 33168920, 2020). "This study demonstrated that TBK1 and GSDMD are upregulated in the SDH of type 1 diabetes mellitus (T1DM) and T2DM-related PDN mouse models." (PMID 39030571, 2024). "By screening small molecules in a transgenic zebrafish model of type 1 diabetes, we identified inhibitors of non-canonical IκB kinases (IKKs), TANK-binding kinase 1 (TBK1) and IκB kinase ε (IKKε), as enhancers of β-cell regeneration." (PMID 30349097, 2018).
viral myocarditis (5 papers, 2024 to 2025). Myocarditis that is caused by an infection with a viral agent. "Recently, TRIM29 was also shown to promote viral myocarditis by enhancing ROS-mediated TBK1 oxidation and inhibition." (PMID 40552295, 2025). "TRIM29 has been reported to contribute to the pathogenesis of viral myocarditis by enhancing ROS-mediated oxidation of TBK1, thereby inhibiting its function." (PMID 39737190, 2024). "Furthermore, TRIM18 knockout has been demonstrated to control viral myocarditis and organ inflammation through the upregulation of TBK1-mediated antiviral immunity." (PMID 40552295, 2025).
Arthritis (4 papers, 2012 to 2025). Inflammation of a joint. "TBK1 recruitment to STING is required not only for IFN signaling that causes embryonic lethality but also for producing inflammatory cytokines that drive arthritis." (PMID 34901991, 2022). "Similarly, DNase II−/−STINGL373A/L373A mice did not manifest any signs of arthritis, specifically indicating that TBK1 recruitment to STING mediates the arthritis development caused by defective DNA clearance." (PMID 34901991, 2022).
colon cancer (4 papers, 2017 to 2024). "In a recent work, TBK1 was shown to be highly expressed in lung, breast and colon cancers, and subjects with tumors that highly express TBK1 have poor responsiveness to tamoxifen treatment and a high potential for relapse." (PMID 28591144, 2017). "This suggests that PARP7 also regulates mechanisms downstream of TBK1, which agrees with a recent study investigating PARP7 signalling in CT26 colon cancer cells." (PMID 39867896, 2024).
esophageal cancer (4 papers, 2021 to 2024). A primary or metastatic malignant neoplasm involving the esophagus. "In regard to esophageal cancer, RNA-sequencing data analysis and clinical information derived from TCGA database identified DNAJB, BNIP1, VAMP7, and TBK1 (TANK binding kinase 1) as prognostic autophagy-related signatures." (PMID 39273093, 2024).
Hepatitis (4 papers, 2012 to 2025). Inflammation of the liver. "A previous study showed that TBK1 is highly expressed in an LPS-induced hepatitis model." (PMID 33718475, 2021).
latent infection (4 papers, 2019 to 2025). "Notably, US9 is not expressed during latent infection, and a recent study demonstrated that the latent protein UL138 can directly bind to both STING and TBK1, leading to the degradation of STING in lysosomes and the inhibition of TBK1." (PMID 40872823, 2025).
liver cancer (4 papers, 2020 to 2024). An epithelial or non-epithelial malignant neoplasm that arises from the liver. "Furthermore, high TBK1 expression has been shown to induce an immunosuppressive tumor microenvironment by increasing PD-L1 expression and inhibiting CD8+ T cell infiltration in lung, liver cancer, and melanoma." (PMID 38816352, 2024).
osteosarcoma (4 papers, 2017 to 2023). A usually aggressive malignant bone-forming mesenchymal neoplasm, predominantly affecting adolescents and young adults. "TBK1 was successfully targeted in oral squamous cell carcinoma and osteosarcoma leading to a decrease in tumor activity and MDM2 amplifications are known to be involved in tumorigenesis of liposarcoma." (PMID 30006612, 2018). "Inhibition of miR-203 stimulated osteosarcoma cell growth by targeting TBK1, proliferation and RAB22A." (PMID 29228583, 2017). "First of all, we verified that 2’3’-cGAMP also increased the expression level of p-STING, p-IRF3, p-TBK1 and IFN-β in osteosarcoma cells." (PMID 35662245, 2022). "In one publication, neither IKKε nor TBK1 is cleaved by NS3/NS4A when each of these kinases is individually co-transfected with NS3/NS4A into an osteosarcoma cell line UNS3-4A-24." (PMID 36766748, 2023).
ovarian carcinoma (4 papers, 2023 to 2025). A malignant neoplasm originating from the surface ovarian epithelium. "When combined with knockdown of another kinase like EDN2, TBK1 silencing further amplifies paclitaxel sensitivity, increasing apoptosis and cell-cycle arrest, thereby improving paclitaxel effectiveness in ovarian cancer treatment." (PMID 39949780, 2025). "Knockdown of TBK1 enhances paclitaxel sensitivity in ovarian cancer by stabilizing microtubules and disrupting cell cycle progression." (PMID 39949780, 2025). "Then we showed that anti-CD47 therapy combined with olaparib also upregulated STING pathway markers (TBK1 and IFNB) in monocytes cocultured with ovarian cancer cells." (PMID 37468567, 2023). "Furthermore, the phosphorylation levels of TBK1, P65, and IRF3 were significantly elevated in ovarian cancer cells and normal immortalized ovarian epithelial cells treated by both PARPi and Entinostat, indicating the activation of cGAS-STING pathway." (PMID 37063431, 2023).
primary progressive aphasia (4 papers, 2020 to 2025). Primary progressive aphasia (PPA) is a neurodegenerative disorder, characterized by a primary dissolution of language, with relative sparing of other mental faculties for at least the first 2 years of illness. "One study reported the co-occurrence of CHCHD10 and C9orf72 variants in an ALS-FTD patient, and another reported a person carrying both TBK1 and SQSTM1 variants, who was diagnosed with non-fluent variant primary progressive aphasia (nfv-PPA)." (PMID 40170896, 2025).
renal fibrosis (4 papers, 2022 to 2024). A final common manifestation of a wide variety of chronic kidney diseases characterized by glomerulosclerosis and tubulointerstitial fibrosis. "The remaining signalling pathways mediating renal fibrosis are STING/TBK1, IL-4Ra/STAT6, Jmjd3/IRF4, STAT6/PPARα, SETD7, NKT/IL-4, BRP-39, STAT-1/TREM-1, MMP-9/Akt, adiponectin/APK, and JAK3/STAT6." (PMID 39445007, 2024). "The STING/TBK1 signalling pathway has an important role in bone marrow-derived fibroblast activation, macrophage-to-myofibroblast transformation, and renal fibrosis progression." (PMID 39445007, 2024). "Taken together, STING/TBK1 signaling contributes to renal fibrosis by the regulation of myeloid fibroblasts activation and marcophages to myofibroblasts transition." (PMID 35924048, 2022). "We next investigated the effect of pharmacological inhibition of TBK1 on the progression of renal fibrosis in FA nephropathy." (PMID 35924048, 2022). "In this study, we investigated the effect of pharmacological inhibition of STING/TBK1 signaling on renal fibrosis induced by folic acid (FA)." (PMID 35924048, 2022). "Nevertheless, the role of STING/TBK1 pathway and its molecular mechanism in renal fibrosis remains to be further elucidated." (PMID 35924048, 2022). "Recent reports have stated that TBK1 dysfunction by inhibitor significantly played a protective role in inflammatory diseases, such as autoinflammatory arthritis, pathological maternal inflammation, and renal fibrosis, exposing the proinflammatory role of TBK1." (PMID 39030571, 2024). "Furthermore, our findings reveal that STING/TBK1 axis exerts a crucial role in renal fibrosis induced by folic acid." (PMID 35924048, 2022). "In this work, we demonstrated that pharmacological inhibition of STING/TBK1 axis impaired bone marrow-derived fibroblasts activation, impeded macrophages to myofibroblasts transition, and protected against renal fibrosis development in folic acid (FA) nephropathy." (PMID 35924048, 2022). "The interferon gene-stimulating factor/TANK-binding kinase 1 (STING/TBK1) axis is a major regulator of the innate immune response and plays a key role in bone marrow-derived fibroblast activation, MMT, and renal fibrosis progression." (PMID 39445007, 2024). "In this study, we show that TBK1 mediates the signaling of STING and plays a critical role in myeloid fibroblasts activation in renal fibrosis." (PMID 35924048, 2022). "Our findings show that inhibition of TBK1 by GSK8612 prevents ECM accumulation, reduces fibroblasts activation, and delay renal fibrosis progression." (PMID 35924048, 2022). "TANK-binding kinase 1 has a crucial role in the regulation MMT and renal fibrosis." (PMID 38575341, 2024).
Salmonella Infections (4 papers, 2016 to 2023). Infections with bacteria of the genus SALMONELLA. "During Salmonella infection, anti-bacteria autophagy requires the participation of Tbk1 and WIPI-2, and NDP52 initiates selective autophagy through the recruitment of Ulkand Tbk1 kinase complexes." (PMID 32187990, 2020). "Furthermore, treatment with the TBK1 inhibitor BX795 resulted in increased Salmonella counts in MK2 expressing MEFs indicating a role for TBK1 in restricting Salmonella infection." (PMID 37771590, 2023). "This was first revealed for the receptor protein optineurin (OPTN) that becomes phosphorylated by the kinase TANK-binding kinase 1 (TBK1) in response to cellular Salmonella infection and it was shown that preventing this phosphorylation reduced the efficiency of LC3 targeting to invading bacteria." (PMID 31450711, 2019). "The mechanism of TBK1 activation in HeLa cells upon Salmonella infection is not known, but it has been shown that a knockdown of TBK1 increases Salmonella replication in HeLa cells." (PMID 27906974, 2016).
Splenomegaly (4 papers, 2015 to 2024). Abnormal increased size of the spleen. "Myeloid cell-specific inhibition of TBK1 and IKKε caused splenomegaly, neutrophilia, and monocytosis that were dependent on RIPK1 kinase activity, demonstrating that TBK1 and IKKε function in a cell-intrinsic manner to suppress RIPK1-dependent expansion of myeloid cells." (PMID 38167258, 2024). "Interestingly, knocking out TBK1 in this myeloid cell population led to progressive splenomegaly and lymphadenopathy similar to that seen in C9orf72-deficient mice." (PMID 30465257, 2019). "Interestingly, however, at an older age (4 months old), the Tbk1-TKO mice had splenomegaly and higher splenocyte numbers as well as increased numbers of CD4+ and CD8+ T cells in different lymphoid organs and the peripheral blood." (PMID 25606824, 2015). "On necropsy, Ikke-/-Tbk1-/-Ripk1wt/D138N and IkkeK38A/K38ATbk1D135N/D135NRipk1wt/D138N mice, but not Tbk1-/-Ripk1wt/D138N and Tbk1D135N/D135NRipk1wt/D138N mice, displayed splenomegaly, which was partially suppressed by homozygous Ripk1D138N/D138N genetic background." (PMID 38167258, 2024).
Stroke (4 papers, 2020 to 2023). Sudden impairment of blood flow to a part of the brain due to occlusion or rupture of an artery to the brain. "The proteins ULK1, NDP52, and TANK-Binding Kinase 1 (TBK1) are also meaningful targets for stroke therapies through targeting autophagy." (PMID 32630218, 2020). "Stroke leads to upregulation of the DNA sensor STING, activates IFN regulatory factor (IRF3) and TANK-binding kinase 1 (TBK1), and induces IFN-β synthesis." (PMID 36892020, 2023). "Our data revealed that stroke led to upregulation of the DNA sensor STING, activation of TBK1 and IRF3, and induction of the IRF3-dependent IFN-β synthesis." (PMID 32427863, 2020).
acute myeloid leukemia (3 papers, 2020 to 2022). Acute myeloid leukemia (AML) is a group of neoplasms arising from precursor cells committed to the myeloid cell-line differentiation. "Targeting TBK1 pharmacologically or by mRNA knockdown induces apoptosis and reduces cell viability in a subset of acute myeloid leukemia (AML) cells with an activated MYC signaling pathway necessary for survival." (PMID 36523963, 2022). "In acute myeloid leukemia, higher levels of TBK1 and IKKε expression were detected in leukemic cells compared to CD34+ HSPCs isolated from healthy donors." (PMID 35395857, 2022). "However, knowledge is emerging that momelotinib (CYT387), a pharmacological inhibitor of noncanonical IkB kinase/TANK-binding kinase 1 (IKBKE/TBK1) which is used in acute myeloid leukemia, might be able to regulate tumor MYC-dependent survival through YB-1." (PMID 31947591, 2020).
adenomyosis (3 papers, 2021 to 2025). The growth of endometrial tissue inside the muscular wall of the uterine corpus. "Even with limited amount of patients, we are able to identify that TBK‐1 and TNF‐α were correlated with dysmenorrhea, which was consistent with a previous study that NF‐κB DNA‐binding activity was correlated with the severity of dysmenorrhea in adenomyosis." (PMID 34010983, 2021). "The cGAS, STING, TANK‐binding kinase 1 (TBK‐1), interferon‐α (IFN‐α), IFN‐β, and tumor necrosis factor‐α (TNF‐α) mRNA and protein levels in the ectopic endometrial tissue from adenomyosis patients were significantly higher compared with that from the controls in endometrium (p < .05)." (PMID 34010983, 2021).
Allergy (3 papers, 2015 to 2024). An allergy is an immune response or reaction to substances that are usually not harmful. "Conversely our study shows the TKO mice exhibit an increased TH2 profile with the exacerbation of allergic disease in parallel with increased TBK1 phosphorylation." (PMID 39803487, 2024).